ATP11A (ATPase phospholipid transporting 11A)
Description:
Catalytic component of a P4-ATPase flippase complex which catalyzes the hydrolysis of ATP coupled to the transport of aminophospholipids, phosphatidylserines (PS) and phosphatidylethanolamines (PE), from the outer to the inner leaflet of the plasma membrane. Does not show flippase activity toward phosphatidylcholine (PC). Contributes to the maintenance of membrane lipid asymmetry with a specific role in morphogenesis of muscle cells. In myoblasts, mediates PS enrichment at the inner leaflet of plasma membrane, triggering PIEZO1-dependent Ca2+ influx and Rho GTPases signal transduction, subsequently leading to the assembly of cortical actomyosin fibers and myotube formation. May be involved in the uptake of farnesyltransferase inhibitor drugs, such as lonafarnib.
Synonyms: ATPIH; ATPIS; KIAA1021; AUNA2; DFNA84; HLD24
Tractability: Antibody: UniProt places it where antibodies can reach, with high confidence; its Gene Ontology location is reachable by antibodies, with high confidence; UniProt predicts a signal peptide or a membrane-spanning region. PROTAC: ubiquitination databases record sites on it; its protein half-life has been measured.
Gene: Protein-coding gene on chromosome 13 (112,689,911 to 112,887,168, forward strand). Ensembl gene ENSG00000068650.
Subcellular location: Cell membrane; Early endosome; Recycling endosome; Endoplasmic reticulum membrane
Subcellular location (Human Protein Atlas): Vesicles; Golgi apparatus
Pathways (Reactome):
Immune System: Neutrophil degranulation
Transport of small molecules: Ion transport by P-type ATPases
Gene Ontology:
Molecular function: ATPase-coupled intramembrane lipid transporter activity; phosphatidylethanolamine flippase activity; phosphatidylserine flippase activity; phosphatidylserine floppase activity; protein binding; ATP binding; ATP hydrolysis activity; magnesium ion binding; nucleotide binding
Biological process: positive regulation of myotube differentiation; regulation of membrane lipid distribution; phospholipid translocation; aminophospholipid translocation; phospholipid transport
Cellular component: early endosome; endoplasmic reticulum; endoplasmic reticulum membrane; lysosomal membrane; membrane; phospholipid-translocating ATPase complex; plasma membrane; recycling endosome; specific granule membrane; tertiary granule membrane; endomembrane system
Genetic constraint (gnomAD): Loss-of-function variants: 63 observed, 130.36 expected, observed/expected ratio (o/e) 0.48, 90% interval 0.39 to 0.6. The upper end of that interval is the gene's LOEUF score, 0.6, which puts it in group 2 of 6, group 1 being the genes least tolerant of losing a copy. Missense variants: 1,141 observed, 1,324.3 expected, observed/expected ratio (o/e) 0.86, 90% interval 0.82 to 0.9. Synonymous variants: 545 observed, 530.85 expected, observed/expected ratio (o/e) 1.03, 90% interval 0.96 to 1.1.
Gene-disease validity (ClinGen):
ClinGen rates the evidence that ATP11A causes each of these diseases.
autosomal dominant nonsyndromic hearing loss (autosomal dominant): Moderate. Autosomal dominant form of nonsyndromic deafness.
Homologues: Orthologues: chimpanzee ATP11A (98% identical), macaque ATP11A (98% identical), dog ATP11A (93% identical), mouse Atp11a (92% identical), rat Atp11a (92% identical), guinea pig ATP11A (90% identical), pig ATP11A (90% identical), tropical clawed frog atp11a (86% identical), zebrafish atp11a (81% identical), rabbit ATP11A (77% identical), Drosophila melanogaster CG4301 (34% identical), Drosophila melanogaster CG9981 (31% identical), and 3 more. Paralogues in human: ATP11C (63% identical), ATP11B (58% identical), ATP8A2 (34% identical), ATP8B2 (34% identical), ATP8A1 (34% identical), ATP8B4 (34% identical), ATP10B (34% identical), ATP8B1 (34% identical), ATP10D (33% identical), ATP10A (33% identical), ATP8B3 (30% identical), ATP9A (27% identical), and 1 more.
Diseases named in the same sentence as ATP11A in open-access papers:
ATP11A is named in the same sentence as 44 diseases in open-access papers, as found by Europe PMC text mining. Sharing a sentence is not in itself a finding about the gene and the disease. The quoted sentences say what the papers report.
COVID-19 (8 papers, 2023 to 2025). A disease caused by infection with severe acute respiratory syndrome coronavirus 2. "We found significantly lower ATP11A expression in COVID-19 lungs when compared with control lungs, which was concordant with the GWAS and eQTL association as the T allele of rs12585036 was associated with low ATP11A and increased risk of COVID-19." (PMID 39876559, 2025). "We found significantly lower ATP11A expression in COVID-19 lungs when compared to control lungs which was concordant with the GWAS and eQTL association as the T allele of rs12585036 was associated with low ATP11A and increased risk of COVID-19." (PMID 39040187, 2024). "We hypothesize that the protective effect of the T allele of rs12585036 ATP11A regarding the risk of severe COVID-19 specifically in men is due to the fact that female sex hormones, in particular estradiol, lead to increased expression of ATP11A." (PMID 39175753, 2024). "During COVID-19, ATP11A was significantly decreased in AT1s, AT2s, other airway epithelial cells, concordant with the GWAS and eQTL data." (PMID 39876559, 2025). "In summary, we used context-specific eQTL datasets of fibroblasts, monocytes, and lungs affected by smoking and IPF to show that ATP11A and DPP9 were likely causal genes in critically ill COVID-19 and IPF." (PMID 39040187, 2024). "IPF32 and critical illness due to COVID-19 were highly colocalized at the ATP11A and DPP9 sQTL loci with a posterior probability of 1.00." (PMID 37794074, 2023). "Thus, our analyses used three context-specific eQTL datasets to reveal that ATP11A was the likely causal gene associated with the IPF and COVID-19 GWAS signals at rs12585036." (PMID 39876559, 2025). "We subsequently found strong evidence of colocalization between the disease GWAS and the ATP11A-eQTL signals (PP4 = 0.996 with IPF GWAS; 0.995 with COVID-19 GWAS) but weaker support for colocalization between the ATP11A-eQTL signals from the Lung eQTL Study and GTEx lung (PP4 = 0.344)." (PMID 39876559, 2025). "These analyses pointed to higher ATP11A expression from the C allele of rs12585036, in monocytes and in lung tissue from primarily smokers, which increased risk of idiopathic pulmonary fibrosis (IPF) and decreased risk of critically ill COVID-19." (PMID 39876559, 2025). "Thus, our analyses used two context-specific eQTL datasets to reveal that ATP11A was the causal gene associated with the IPF and COVID-19 GWAS signals at rs12585036." (PMID 39040187, 2024). "This study reaffirmed previous findings that MUC5B, DPP9, and ATPase phospholipid transporting 11A (ATP11A) all represent shared genetic associations for both IPF risk and severity of COVID-19; however, crucially the analysis shows these findings are unified by a single causal variant." (PMID 37759460, 2023). "In conclusion, we have used genetic determinants of alternative splicing and COVID-19 outcomes obtained from large-scale studies and found compelling evidence that splicing events in OAS1, ATP11A, DPP9, NPNT, MUC1, and PMF1 have causal effects on COVID-19 severity and susceptibility." (PMID 37794074, 2023). "Taken together, these expression evidence suggests that the transcriptional splicing—COVID-19 outcome relationships for ATP11A, DPP9, MUC1, and NPNT were likely to be relevant in lung tissue and these signals may be especially important in alveolar epithelial cells." (PMID 37794074, 2023). "An LD proxy of rs12585036, rs9577395 (r2 = 0.99) was a conditionally independent eQTL for ATP11A in tissues of unclear relevance to IPF and COVID-19 (aorta, skin, and small intestine)." (PMID 39876559, 2025). "Altogether, these findings support the relevance of ATP11A and DPP9 in IPF and COVID-19 pathogenesis." (PMID 39876559, 2025). "An LD proxy of rs12585036, rs9577395 (r2=0.99) was a conditionally independent eQTL for ATP11A in tissues of unclear relevance to IPF and COVID-19 (aorta, skin, small intestine)." (PMID 39040187, 2024).
COVID-19 (continued). "In 23 lung COVID-19 autopsy donor tissue samples from GSE17166820, the expression of ATP11A, DPP9, MUC1, and NPNT were also enriched in alveolar type 1 and 2 epithelial cells." (PMID 37794074, 2023). "Last, we show that ATP11A, DPP9, NPNT, and MUC1 are highly expressed in lung alveolar epithelial cells, both in COVID-19 uninfected and infected samples." (PMID 37794074, 2023). "Shared genetic signals between IPF and severe COVID-19 were identified near MUC5B, DPP9 and ATP11A, although the signals at MUC5B and ATP11A had opposite effects on the risk for the two diseases." (PMID 37410458, 2023). "We propose two mechanisms that could explain ATP11A’s involvement in the pathogenesis of IPF and COVID-19." (PMID 39876559, 2025). "We identify that alternative splicing in lung, rather than total expression of OAS1, ATP11A, DPP9 and NPNT, is associated with COVID-19 severity." (PMID 37794074, 2023). "Thus, we propose that ATP11A may affect IPF and COVID-19 by functioning in both epithelial and myeloid cells and by impairing cell death and immune pathways." (PMID 39876559, 2025). "We subsequently found evidence of colocalization between the disease GWAS and the ATP11A-eQTL signals (PP4 = 0.996 with IPF GWAS; 0.995 with COVID-19 GWAS) but lack of colocalization between the ATP11A-eQTL signals from the Lung eQTL Study and GTEx lung (PP4 = 0.344)." (PMID 39040187, 2024). "Thus, we propose that ATP11A may affect IPF and COVID-19 by functioning in both epithelial and myeloid cells and eliciting impaired cell death and immune pathways." (PMID 39040187, 2024). "However, in tissues relevant to IPF and COVID-19 (EBV-transformed lymphocytes, cultured fibroblasts, lung, and whole blood), we found modest colocalization of the GWAS and ATP11A-eQTL signals in whole blood (PP4 = 0.621 with IPF GWAS; 0.749 with COVID-19 GWAS)." (PMID 39040187, 2024). "However, in another study which measured gene expression in whole blood (GSE172114), we found that ATP11A expression was higher in patients diagnosed with critically ill COVID-19 when compared to those with non-critically ill COVID-19, which could be due to an increase in myeloid lineage cells." (PMID 39040187, 2024).
colorectal cancer (7 papers, 2016 to 2024). A primary or metastatic malignant neoplasm that affects the colon or rectum. "A high level of ATP11A was proposed as a novel predictive marker for metachronous metastasis of colorectal cancer." (PMID 37686603, 2023). "A previous study reported that ATP11A is a predictive prognosis marker of colorectal cancer (CRC) because its mRNA level was significantly higher in CRC tissues compared to normal tissues." (PMID 35345586, 2022). "Additionally, changes in ATP11A have implications beyond diabetes, potentially impacting disease-free survival rates in colorectal cancer, notably affecting schizophrenia patients, who face a 50% higher risk of cancer-related mortality." (PMID 39202552, 2024). "For example, high ATP11A expression was an independent predictor of colorectal cancer." (PMID 39247595, 2024). "One study identified ATP11A as a predictive prognosis marker of colorectal cancer (CRC)." (PMID 35345586, 2022). "Gene expression for another P4-ATPase, ATP11A, was assessed in 7 colorectal cancer cell lines and 95 paired cases of colorectal cancer and non-cancerous regions." (PMID 37686603, 2023). "ATP11A, which is a member of class 6 of P4-ATPases family is a possible negative predictive marker for metachronous metastasis in colorectal cancer patients and may confer resistance to cancer treatment with farnesyltransferase inhibitors." (PMID 27347675, 2016).
lung disease (5 papers, 2016 to 2025). "Similarly, in a recent genome-wide association study ATP11A was associated with fibrotic idiopathic interstitial pneumonias, a group of pulmonary disorders associated with inflammation and fibrosis." (PMID 27628304, 2017). "Examination of eQTL data from isolated cell types and lung disease states was necessary to reveal DPP9 and ATP11A as two additional causal genes." (PMID 39040187, 2024). "Of interest, DNA methylation of ATP11A (cg11702988) positively correlated with lung function (FEV1 and FVC) and BMI, and negatively correlated with lung disease severity (mild, intermediate, and severe CF patients) and with the presence of chronic P. aeruginosa." (PMID 33808877, 2021).
acute myeloid leukemia (3 papers, 2023 to 2024). Acute myeloid leukemia (AML) is a group of neoplasms arising from precursor cells committed to the myeloid cell-line differentiation. "Further, low levels of ATP11A expression/methylation were identified as independent prognostic factors for acute myeloid leukemia (AML)." (PMID 38382846, 2024). "Furthermore, low levels of ATP11A expression/methylation were identified as independent prognostic factors for another blood malignancy, acute myeloid leukemia (AML) using the methylation array data and mRNA array data from the Gene Expression Omnibus (GEO) database." (PMID 37686603, 2023).
idiopathic interstitial pneumonia (3 papers, 2014 to 2023). A class of diffuse lung diseases that typically affect the pulmonary interstitium, although some also have a component affecting the airways (for instance, Cryptogenic organizing pneumonitis). "Moreover very recently the ATP11A gene, which encodes for another ATP-binding cassette transporter, has been identified as a risk factor for fibrotic idiopathic interstitial pneumonias in a genome-wide association study on 1616 cases." (PMID 24730976, 2014).
pancreatic cancer (3 papers, 2022 to 2024). "The main aim of this study was to identify ATP11A, which is associated with the biological behavior of pancreatic cancer, and elucidate its relationship with Numb and the underlying mechanism behind this relationship." (PMID 35345586, 2022). "In summary, ATP11A is highly expressed in pancreatic carcinoma and is associated with adverse prognosis." (PMID 35345586, 2022). "At present, ATP11A has been studied in several cancer types, including prostate cancer 16, colon cancer 17 and pancreatic cancer." (PMID 39247595, 2024). "In a comparison of pancreatic cancer and paracancerous tissues, ATP11A mRNA and protein levels were significantly higher in cancer." (PMID 37686603, 2023). "First, data retrieved from The Cancer Genome Atlas (TCGA) and Genotype-Tissue Expression (GTEX) databases was used to investigate the expression of ATP11A mRNA and its relationship with Numb mRNA in pancreatic cancer." (PMID 35345586, 2022). "At the mRNA level, the expression of ATP11A in pancreatic cancer tissues was significantly higher than in normal pancreatic tissues (P < 0.001)." (PMID 35345586, 2022). "Transwell assay results showed that increased ATP11A expression can increase the invasion and migration ability of pancreatic cancer cells, and vice versa." (PMID 35345586, 2022). "In this study, the role of ATP11A and its association with Numb PRRL in pancreatic cancer (PAAD) was investigated." (PMID 35345586, 2022). "Western blot assays on 31 pairs of pancreatic cancer tissues and paracancerous tissues, and immunohistochemical assays on 81 pancreatic cancer specimens were performed in order to verify the expression of ATP11A in pancreatic cancer at the protein level." (PMID 35345586, 2022). "ATP11A is significantly upregulated in pancreatic cancer tissues, where it promotes the invasion and migration ability of pancreatic cancer cells." (PMID 35345586, 2022). "Next, ATP11A was overexpressed or knocked down to observe its effects on the invasion and migration ability of pancreatic cancer cells and the changes of downstream proteins." (PMID 35345586, 2022). "The immunohistochemical results of 81 pancreatic cancer cases showed that ATP11A was mainly expressed in the ductlike structure of pancreatic cancer, and was expressed in the cytomembrane and cytoplasm of pancreatic cancer cells." (PMID 35345586, 2022). "The results showed that the expression of ATP11A was significantly higher in pancreatic cancer tissues than in paracancerous tissues (P = 0.0009)." (PMID 35345586, 2022). "In this study, the mRNA level of ATP11A was significantly higher in pancreatic cancer tissues than in normal tissues, and there was a strong correlation between the mRNA level of ATP11A and Numb." (PMID 35345586, 2022). "Western blot and immunohistochemical results confirmed that the ATP11A protein level was significantly higher in pancreatic cancer tissues than in adjacent tissues, and the ATP11A protein level was correlated with tumor stage." (PMID 35345586, 2022). "At the protein level, ATP11A expression in pancreatic cancer tissues was significantly higher than that in paracancerous tissues (P = 0.0009), and high ATP11A expression was also correlated with a worse prognosis." (PMID 35345586, 2022). "The expression of ATP11A was higher in cancer tissues than in paracancerous tissues, and was associated with the AJCC stage of pancreatic cancer (P = 0.045)." (PMID 35345586, 2022). "The expression of ATP11A protein in 31 pancreatic cancer tissues and corresponding paracancerous tissues was measured using western blot." (PMID 35345586, 2022). "Moreover, ATP11A promoted the invasion and migration of cultured pancreatic cancer cells via TGFB-dependent epithelial-mesenchymal transition (EMT)." (PMID 37686603, 2023).
pancreatic cancer (continued). "Numb PRRL was specifically knocked down after the overexpression of ATP11A, then observing whether the effect of ATP11A overexpression on the biological behavior of pancreatic cancer cells was recovered." (PMID 35345586, 2022). "Furthermore, ATP11A affects the epithelial-to-mesenchymal transition (EMT) of pancreatic cancer by regulating the TGFB dependent Numb PRRL-ZEB1/Snail2 pathway." (PMID 35345586, 2022). "After confirming the association between ATP11A and Numb PRRL and the promoting effect of ATP11A on EMT, we decided to explore the expression of Numb PRRL in pancreatic cancer tissues and whether Numb PRRL affects EMT." (PMID 35345586, 2022). "Similar results in two types of pancreatic cancer cells were obtained, suggesting that ATP11A may influence the biological behavior of tumours in pancreatic carcinoma by regulating Numb PRRL." (PMID 35345586, 2022). "Moreover, our results showed that ATP11A can promote the invasion and migration of pancreatic cancer cells." (PMID 35345586, 2022). "Moreover, we found that ATP11A can promote the epithelial-to-mesenchymal transition (EMT) of pancreatic cancer." (PMID 35345586, 2022). "After transfection of PANC-1 and SW1990 cells with ATP11A overexpression plasmid, significant changes were found in cell morphology, which indicated that the overexpression of ATP11A promoted the occurrence of EMT in pancreatic cancer cells." (PMID 35345586, 2022). "In pancreatic cancer tissues, ATP11A expression was remarkably higher than in normal tissues (P < 0.001)." (PMID 35345586, 2022). "Finally, pancreatic cancer cells were stimulated with TGFB1 and ATP11A expression was examined to explore whether the effect of ATP11A on EMT was TGFB dependent." (PMID 35345586, 2022).